PDLIM2 (PDZ and LIM domain 2)
Diseases named in the same sentence as PDLIM2 in open-access papers (continued):
Sharing a sentence is not in itself a finding about the gene and the disease.
tumor (31 papers, 2011 to 2025). "One key mechanism underlying PDLIM2’s tumor-suppressive effects involves the negative regulation of the nuclear factor kappa B (NF-κB) and signal transducer and activator of transcription 3 (STAT3) signaling pathways." (PMID 40948895, 2025). "PX-478 treatments significantly reduced the tumor growth promotion caused by PDLIM2 knockdown in LLC cells." (PMID 38880883, 2024). "Particularly, in BLCA and KIRP, PDLIM2 is mainly associated with immunosuppression in tumor tissues." (PMID 35121770, 2022). "PDLIM2 expression was associated with the tumor mutation burden in 12 cancer types and microsatellite instability in 5 cancer types." (PMID 35121770, 2022). "PDLIM2 is frequently disrupted in various cancers, and its expression is associated with both tumorigenesis and tumor suppression." (PMID 35121770, 2022). "We assessed the correlation between PDLIM2 expression and immune-associated gene expression, immune score, tumor mutation burden, and DNA microsatellite instability." (PMID 35121770, 2022). "Based on this result, the expression levels of most marker sets of monocytes, tumor-associated macrophages (TAMs), M2 macrophages, dendritic cells, and T cell exhaustion were positively correlated with PDLIM2 expression." (PMID 35121770, 2022). "Pdlim2 is reported to be associated with tumor suppression and tumorigenesis, but its function in the nervous system remains unknown." (PMID 36732866, 2023). "To determine whether PDLIM2 is associated with a particular immune cell subset, we analyzed the phenotype of the tumour-infiltrating cells, first focusing on T cell populations." (PMID 36531051, 2022). "Notably, the expression of PDLIM2 was significantly associated with immune checkpoint expression in most tumor types." (PMID 35121770, 2022). "On the other hand, ROS released by tumor cells may contribute to PDLIM2 downregulation in tumor-associated cells, such as TAMs." (PMID 33539325, 2021). "PDLIM2 was repressed in tumor-associated macrophages (TAMs)/AMs." (PMID 33539325, 2021). "Methylation-mediated gene silencing serves as a prevalent mechanism for inhibiting PDLIM2 in tumor tissues." (PMID 40476213, 2025). "This review will discuss various aspects including the gene expression profile of PDLIM2, along with its structure distribution patterns and its involvement in tumor development signaling pathways." (PMID 40476213, 2025). "The PDZ-LIM domain-containing protein PDLIM2 serves as a unique tumor suppressor and immune modulator." (PMID 41346604, 2025). "This approach uses systemically delivered nanoparticles containing PDLIM2-expressing plasmids to re-establish tumor suppressive and immune-stimulating functions." (PMID 40948895, 2025). "These distinct effects of PDLIM2 on the regulation of tumor growth suggest its involvement in a more complex regulatory network than currently understood, highlighting the need for further research in this area." (PMID 38880883, 2024). "PDLIM2 has been reported to exert varying effects and employ diverse mechanisms in controlling tumor growth across different cancer types." (PMID 38880883, 2024). "Another important clinical characteristic of PDLIM2 nanotherapy is its tumor-specificity and high safety profile." (PMID 39718207, 2024). "It should be pointed out that the tumor delivery efficiency of PDLIM2-expression or control plasmid nanoparticles was similarly high." (PMID 39718207, 2024). "To further investigate the impact of PDLIM2 downregulation on tumor growth and the expression of TCA cycle-related genes within tumors, we utilized an allograft mouse model for study." (PMID 38880883, 2024). "(H) Percentage of tumor types spontaneously developed in Pdlim2-/- and Pdlim2+/- mice showing a majority of lung tumors." (PMID 39718207, 2024). "PDZ-LIM domain-containing protein 2 (PDLIM2), an essential tumor suppressor and immunomodulator, was the first cellular protein identified to negatively regulate Tax." (PMID 38722890, 2024).
tumor (continued). "The increased accumulations of succinate and mtROS inactivate PHD, consequently upregulating HIF-1α, which significantly contributes to tumor growth promotion in PDLIM2-knockdown conditions." (PMID 38880883, 2024). "The PDZ-LIM domain-containing protein PDLIM2 is a common tumor suppressor and a key immune modulator." (PMID 39080804, 2024). "(A) TCGA data showing PDLIM2 repression in over 90% of lung tumors if using 50% of the expression level in normal lung tissues as the cut-off (NL, n=110; Tumor, n=1019)." (PMID 39718207, 2024). "In the animal study, the orally administered HIF-1α inhibitor, PX-478, significantly reduces PDLIM2 knockdown-promoted tumor growth." (PMID 38880883, 2024). "Whereas PDLIM2 nanotherapy increased MHC-I expression on tumor cells, which is critical for better recognition and killing of tumor cells by CD8+ CTLs, chemotherapy alone or its combination with anti-PD-1 failed to do so." (PMID 39718207, 2024). "(G) Kaplan-Meier tumor-free survival curve showing increased spontaneous tumors in Pdlim2-/- and Pdlim2+/- mice compared to WT mice." (PMID 39718207, 2024). "PDLIM2 exerts tumor-suppressive effects by inhibiting HCC cell proliferation, migration, invasion, EMT, and colony formation through the inhibition of β-catenin activity." (PMID 37894409, 2023). "When TNBC cases were separately analyzed (METABRIC n=320 and TCGA n=190), there was a significantly higher estimated level of M2 macrophages observed in METABRIC tumours with higher PDLIM2 mRNA expression." (PMID 36531051, 2022). "Increased expression of PDLIM2 was significantly correlated with the tumor grade in seven types of tumors." (PMID 35121770, 2022). "In this scenario, suppression of PDLIM2 in cell and murine models has been shown to impair polarized cell migration and metastatic potential of tumour cells in vitro and in vivo." (PMID 36531051, 2022). "CD206 was significantly higher in TNBC tumours with PDLIM2-positive stroma than in those with PDLIM2-negative stroma, while CD163 was higher, but not quite reaching significance." (PMID 36531051, 2022). "Paradoxically, PDLIM2 can be either a tumor suppressor or a tumor promoter, depending on the cellular context." (PMID 35707002, 2022). "In this analysis, PDLIM2 expression was significantly correlated with the tumor stage in seven types of cancers." (PMID 35121770, 2022). "Previous studies focused on the prognostic role of tumor mutational burden (TMB) in immunotherapy in many cancer types; here, we counted the TMB of each tumor sample and analyzed the relationship between PDLIM2 expression and TMB in 12 different cancer types." (PMID 35121770, 2022). "We examined the usefulness of PDLIM2 as a prognostic biomarker related to tumor immune interactions and its role as a therapeutic target in combined immunotherapy in 33 cancers." (PMID 35121770, 2022). "Specifically, high PDLIM2 mRNA expression was positively correlated with tumor stage in BLCA, kidney renal clear cell carcinoma, LIHC, KIRP, COAD, and LUSC." (PMID 35121770, 2022). "PDLIM2 acts as a tumor suppressor by inhibiting cancer-related genes and is involved in antigen presentation and T cell activation." (PMID 35707002, 2022). "Our previous report on high levels of PDLIM2 expression in a large proportion of TNBC cases, and its association with beta catenin activity and adhesion signalling in the tumour cells, suggested a role in TNBC aggressiveness." (PMID 36531051, 2022). "A previous study showed that upregulation of PDLIM2 in cancer cells impaired anchorage-independent growth both in vitro and in vivo, indicating a tumor-suppressive role." (PMID 35707002, 2022). "Tumor microenvironment analysis revealed that the PDLIM2 mRNA expression was positively correlated with the immune score, stromal score, and various tumor infiltrating immune cells." (PMID 35707002, 2022). "In the course of the TNBC study, it was noted that PDLIM2 was highly expressed in the stroma of PDLIM2-expressing tumours." (PMID 36531051, 2022).
tumor (continued). "Tumor-derived sEVs carrying miR-222 promote BC cell migration and invasion by downregulating the tumor suppressor PDLIM2 and activating the NF-κB signaling pathway." (PMID 36499561, 2022). "Here, we identified the tumor suppressor PDZ-LIM domain–containing protein 2 (PDLIM2) as a checkpoint of alveolar macrophages (AMs) important for lung tumor suppression." (PMID 33539325, 2021). "The epigenetic genetic repression of PDLIM2 have influenced the MAPK/ERK pathway depending on the tissue-specific tumor microenvironment." (PMID 34203785, 2021). "This is in contrast to the tumor suppression by cancer cell–intrinsic PDLIM2, which depends on both STAT3 and RelA." (PMID 33539325, 2021). "PDLIM2 acts as a tumor suppressor by inhibiting cancer-related genes and increasing the expression of genes involved in antigen presentation and T-cell activation." (PMID 34203785, 2021). "Altogether, these data demonstrated that PDLIM2 is a bona fide tumor suppressor that is particularly important for lung tumor suppression." (PMID 31757943, 2019). "PDLIM2 exhibits tumor suppressor activity, but is also highly expressed in certain invasive cancers." (PMID 26191041, 2015). "PDLIM2 exerts its tumor suppressor role and immune regulation effect through multiple mechanisms." (PMID 41000764, 2025). "Thus, PDLIM2 is a haploinsufficient tumor suppressor that is particularly important for lung tumor suppression." (PMID 39718207, 2024). "PDLIM2 has been established as a tumor suppressor and serves as a ubiquitin ligase for P65." (PMID 38992675, 2024). "Consistently, PDLIM2 knockdown cells exhibited an accelerated tumor growth rate in mice." (PMID 38880883, 2024). "We further analyzed the relationship between PDLIM2 expression and tumor immune cell infiltration." (PMID 35121770, 2022). "The correlation between PDLIM2 expression and immune cell marker genes suggests that PDLIM2 can control the infiltration and interaction of immune cells in the tumor microenvironment, and Treg-like immunosuppression can be induced by inducing Foxp3 expression in naïve T cells." (PMID 35121770, 2022). "The presence of PDLIM2 in tumour stromal cells in this study raised the question whether PDLIM2 is associated with lymphocytes or macrophages, where it has known regulatory functions that might influence the tumour microenvironment." (PMID 36531051, 2022). "Furthermore, in vitro and in vivo results demonstrated that knockdown of PDLIM2 significantly inhibited tumor cell growth and invasiveness in human CRPC-like cells." (PMID 35707002, 2022). "To further establish the phenotype of the tumour-associated macrophages (TAMs) that express PDLIM2, we analyzed the percentage of PDLIM2-positive or -negative tumours that expressed low or medium/high levels of CD163." (PMID 36531051, 2022). "The expression of PDLIM2 is related to both tumor inhibition and tumorigenesis." (PMID 35121770, 2022). "However, in both datasets, higher levels of M2 macrophage infiltration were clearly observed in tumours with higher PDLIM2 mRNA expression." (PMID 36531051, 2022). "PDLIM2 expression was negatively correlated with tumor purity." (PMID 35121770, 2022). "Finally, IHC analysis further implicated the protein level of PDLIM2 was upregulated in PRAD and acts as a novel potential biomarker in predicting tumor progression." (PMID 35707002, 2022). "However, PDLIM2 knockout mice had a similar tumor formation rates comparing wild-type mice when observed in the colon." (PMID 34203785, 2021). "In addition to the tumor, it was found that the regulation of PDLIM2 expression of the individual was also involved in the growth and proliferation of the tumor." (PMID 34203785, 2021). "MAPK/ERK activation is associated with angiogenic growth factor signaling in tumor cells, suggesting that PDLIM2 may act as an oncogenic protein that promotes tumor formation and metastasis by activating MAPK/ERK." (PMID 34203785, 2021).
tumor (continued). "This suggests that PDLIM2 may play several roles in regulating tumor growth and progression in various organs and circumstances." (PMID 34203785, 2021). "Given high ROS production in tumor cells, this mechanism may also contribute to PDLIM2 repression in tumor cells." (PMID 33539325, 2021). "The role of PDLIM2 in tumor formation and inhibition is controversial." (PMID 34203785, 2021). "Moreover, we confirmed that the specific inhibition of PDLIM2 resulted in significantly reduced tumor growth in human CRPC xenograft models." (PMID 34203785, 2021). "Here, PDLIM2 inhibition resulted in the inhibition of tumor growth in an in vivo metastatic kidney cancer xenograft model, indicating that PDLIM2 may be a new therapeutic target for metastatic kidney cancer." (PMID 34203785, 2021). "In many previous studies, PDLIM2 has been reported to be a tumor suppressor." (PMID 34203785, 2021). "Furthermore, in expanding on these domains, PDZ and LIM domain protein 2 (PDLIM2/mystique/SLIM) was found to be dysregulated with overexpression in several tumor samples." (PMID 33346248, 2020). "Additionally, tumorigenicity was significantly reduced in PDLIM2-transfected cells 1 month after transfection, whereas rapid tumor growth was observed in the control groups (P < 0.05)." (PMID 26863570, 2016). "Importantly, suppression of PDLIM2, a putative tumor suppressor, is thought to contribute to tumor cell migration." (PMID 27458446, 2016). "Furthermore, the suppression of PDLIM2 has been found to reverse the epithelial-to-mesenchymal phenotype and to inhibit tumor growth in vivo, suggesting that targeting these pathways might offer viable therapeutic strategies for TNBC." (PMID 38473804, 2024). "However, PDLIM2 has also been reported as a tumor-promoting gene in certain cancer types." (PMID 38880883, 2024). "There was a marked correlation between the expression of PDLIM2 and marker genes of Treg and T cell exhaustion, particularly in KIRP, which may lead to immune dysfunction and poor prognosis in patients with cancer, confirming the role of PDLIM2 in tumor immune escape." (PMID 35121770, 2022). "The principle underlying the role of PDLIM2 in tumor growth and metastasis is not yet clear." (PMID 34203785, 2021). "PDLIM2, a PDZ-LIM domain-containing protein expressed highest in the lung and immune cells, serves as a unique tumor suppressor and immune modulator, mainly by turning off the activation of the master transcription factors NF-κB and STAT3." (PMID 41000764, 2025). "PDLIM2 repression in tumor cells thus results in the persistent activation of STAT3 and RelA, leading to MHC-I downregulation and high expression of tumor growth-related genes." (PMID 39718207, 2024). "Not only that, PDLIM2 also promotes the degradation of NF-κB and STAT3 and inhibits the development of tumor resistance." (PMID 37894409, 2023). "Repression of PDLIM2 has been shown to continuously activate nuclear factor-κB and STAT3, eventually leading to tumorigenesis and tumor maintenance." (PMID 35121770, 2022). "Immune cells in the tumor microenvironment play a vital role in the progression of PRAD, and PDLIM2 has been reported to participate in immune process." (PMID 35707002, 2022). "Moreover, PDLIM2 may be a valuable therapeutic target for tumor immunotherapy in 33 cancer types." (PMID 35121770, 2022). "The rate of positive PDLIM2 expression was significantly higher in PRAD tissues (32.3%, 10/31) than in tumor-adjacent tissues (9.7%, 3/28) (P = 0.029)." (PMID 35707002, 2022). "Overall, we conclude that M2 macrophage infiltration is enhanced in PDLIM2- positive tumour stroma, with CD163+ and CD206+ macrophages more strongly represented in these tumours than in PDLIM2-negative stroma." (PMID 36531051, 2022). "In addition, PDLIM2 may contribute to the ability of tumor cells to migrate." (PMID 34203785, 2021).
tumor (continued). "The preclinical data of this study showed that the regulation of PDLIM2 expression, which regulates the MAPK/ERK signaling pathway, is involved in tumor growth and proliferation in metastatic renal cancer." (PMID 34203785, 2021). "To verify the relationship between the oncogenic function of the PDLIM2 gene and metastasis in vivo, we established kidney orthotopic tumor model using GFP/lucirease expressing RenCa in control (Balb/c) and PDLIM2-knockout mice." (PMID 34203785, 2021). "Especially, the two tumor suppressors SP140 predicted for all three drugs and PDLIM2 predicted for cladribine and fludarabine could be of greater general interest for future experiments." (PMID 41146244, 2025). "In addition, protein levels in tumor cell lysates and tumor tissues investigated by immunoblotting and IHC staining respectively, revealed an increase in HIF-1α level in tumors derived from PDLIM2 knockdown cells, and which was blocked by PX-478." (PMID 38880883, 2024). "Combining with PDLIM2 nanotherapy further significantly decreased tumor burden, although the decrease in tumor number failed to reach statistical significance." (PMID 39718207, 2024). "Presently, there is no consensus on how PDLIM2 can act as a tumor suppressor in some cancer types while promoting tumor growth in others." (PMID 38880883, 2024). "Reduction of PDLIM2 in these cases results in the constitutive activation of transcription factors, including NF-κB and STAT3, leading to increased tumor inflammation and supporting tumor growth." (PMID 38880883, 2024). "This demonstrated higher CD68 in the stroma of TNBC PDLIM2-positive tumours than in PDLIM2-negative tumours." (PMID 36531051, 2022). "More than 85% of PDLIM2-positive TNBC tumours expressed moderate or high CD68 expression compared to 65% of the PDLIM2 negative tumours." (PMID 36531051, 2022). "Importantly, out of all PDLIM2-positive tumours, 40% expressed high levels of CD68 compared to less than 10% of the PDLIM2-negative tumours." (PMID 36531051, 2022). "Expression levels of CD206 and CD163 were higher in the stroma of PDLIM2-positive than in PDLIM2-negative TNBC tumours, but these differences were not significant." (PMID 36531051, 2022). "Higher scores for moderate/high expression of CD163 were observed in PDLIM2-positive stroma and intra-tumour infiltrates than in PDLIM2-negative tumours, while the scores for low CD163 expression were similar." (PMID 36531051, 2022). "The results demonstrated significantly higher numbers of CD14+ and CD68+ cells in the tumour infiltrate of PDLIM2-positive tumours and in PDLIM2-positive stroma than in either PDLIM2-negative tumours or stroma." (PMID 36531051, 2022). "When TNBC cores were analyzed separately, similar levels of staining for each T cell subset were observed in PDLIM2-positive and -negative tumours and stroma." (PMID 36531051, 2022). "Epigenetic repression of PDLIM2 has been shown in tumor cells, but its regulation has not been examined in nonmalignant or immune cells." (PMID 33539325, 2021). "The role of HIF-1α in the tumor-promoting effect of PDLIM2 knockdown had not been reported." (PMID 38880883, 2024). "Indeed, within serial sections of PDLIM2-positive tumours, there was considerable overlap in the profile of CD68 and PDLIM2 stromal staining, while the expression of CD68 within the tumour was similar in all cores." (PMID 36531051, 2022). "However, high expression of PDLIM2 protein was not correlated with age or various tumor biomarkers in patients with PRAD (P > 0.05), except Ki67 (P = 0.034)." (PMID 35707002, 2022). "Our next objective was to investigate macrophage populations in the breast TMA by first analyzing the expression of CD14 (monocytes), CD68 (all macrophages), and CD163 (M2 macrophages), and further stratifying the expression of these markers within PDLIM2-positive and -negative tumours." (PMID 36531051, 2022).